FABP1 (fatty acid binding protein 1)
Description:
Plays a role in lipoprotein-mediated cholesterol uptake in hepatocytes. Binds cholesterol. Binds free fatty acids and their coenzyme A derivatives, bilirubin, and some other small molecules in the cytoplasm. May be involved in intracellular lipid transport (By similarity).
Synonyms: L-FABP; FABPL
Tractability: Small molecule: a structure with a bound ligand is known; it has a high-quality binding pocket; it belongs to a druggable protein family. PROTAC: its protein half-life has been measured; a small molecule that binds it is known.
Target class: Fatty acid binding protein family; Auxiliary transport protein
Chemical probes: FENOFIBRATE
Gene: Protein-coding gene on chromosome 2 (88,122,982 to 88,128,115, reverse strand). Ensembl gene ENSG00000163586.
Subcellular location: Cytoplasm
Subcellular location (Human Protein Atlas): Cytosol; Nucleoplasm
Pathways (Reactome):
Metabolism: Heme degradation; PPARA activates gene expression; Regulation of lipid metabolism by PPARalpha; Triglyceride catabolism
Cellular responses to stimuli: Cytoprotection by HMOX1
Gene Ontology:
Molecular function: antioxidant activity; molecular carrier activity; protein binding; fatty acid binding; lipid transporter activity; long-chain fatty acid transmembrane transporter activity; cholesterol binding; chromatin binding; lipid binding; lipid transfer activity; long-chain fatty acyl-CoA binding; sterol binding
Biological process: cellular detoxification; cellular response to hydrogen peroxide; cellular response to hypoxia; fatty acid transport; heme catabolic process; regulation of lipid metabolic process; triglyceride catabolic process; cellular oxidant detoxification; intermembrane lipid transfer; lipid transport; long-chain fatty acid transport
Cellular component: cytosol; extracellular exosome; nucleoplasm; nucleus; peroxisomal matrix; cytoplasm
Genetic constraint (gnomAD): Loss-of-function variants: 10 observed, 11.35 expected, observed/expected ratio (o/e) 0.88, 90% interval 0.54 to 1.49. The upper end of that interval is the gene's LOEUF score, 1.49, which puts it in group 6 of 6, group 1 being the genes least tolerant of losing a copy. Missense variants: 106 observed, 121.14 expected, observed/expected ratio (o/e) 0.88, 90% interval 0.75 to 1.03. Synonymous variants: 38 observed, 48.04 expected, observed/expected ratio (o/e) 0.79, 90% interval 0.61 to 1.04.
Homologues: Orthologues: chimpanzee FABP1 (100% identical), dog FABP1 (91% identical), pig FABP1 (90% identical), mouse Fabp1 (84% identical), macaque FABP1 (82% identical), tropical clawed frog fabp1 (69% identical), zebrafish fabp1a (64% identical), zebrafish fabp1b.1 (59% identical), rat Fabp1 (57% identical), zebrafish fabp1b.2 (40% identical), Caenorhabditis elegans lbp-7 (24% identical), Caenorhabditis elegans lbp-8 (22% identical). Paralogues in human: FABP6 (35% identical), CRABP2 (30% identical), FABP7 (29% identical), FABP3 (28% identical), CRABP1 (28% identical), RBP2 (26% identical), RBP7 (26% identical), PMP2 (25% identical), RBP1 (25% identical), FABP9 (24% identical), FABP12 (23% identical), FABP5 (23% identical), and 3 more.
Diseases named in the same sentence as FABP1 in open-access papers:
FABP1 is named in the same sentence as 188 diseases in open-access papers, as found by Europe PMC text mining. Sharing a sentence is not in itself a finding about the gene and the disease. The quoted sentences say what the papers report.
Hepatic steatosis (59 papers, 2008 to 2025). Steatosis is a term used to denote lipid accumulation within hepatocytes. "We demonstrated that curcumin, alone and associated with andrographolide, reduces FABP1 expression, which has just been identified as a target for the medical treatment of fatty liver disease." (PMID 36770927, 2023). "In the liver, increased expression of Pparγ, Scd1, Srebp, and Fabp1 is associated with hepatic steatosis." (PMID 33983968, 2021). "The present findings suggest that development of an FABP1/LFABP inhibitor might prove useful in preventing both obesity-associated liver steatosis and the decline in exercise performance." (PMID 40077623, 2025). "Repression of FABP1 expression was associated with fatty liver disease in both mice and humans and could be a contributing factor to the development of fatty liver in mice chronically fed with uridine." (PMID 26789264, 2016). "Therefore, FABP1 plays a critical role in regulating the metabolism underlying hepatic steatosis." (PMID 38791126, 2024). "In a rat model of fatty liver generated by HFD, FABP1 expression was dramatically increased, which impaired fatty acid metabolism and was crucial to the onset and progression of fatty liver disease." (PMID 40431421, 2025). "As shown, CD36-knockout mice were protected against HFD-induced liver steatosis and reduced expression of FABP1 resulting in decreased intracellular lipid-binding capacity and reduced lipotoxicity." (PMID 36705799, 2024). "FABP1 deletion in hepatocytes attenuates both diet-induced hepatic steatosis and fibrogenesis, characteristics of NASH, whereas HSC-specific FABP1 deletion did not alter the fibrogenesis." (PMID 37207357, 2023). "Overexpression of Fabp1 exacerbates hepatic steatosis, while hepatic lipid accumulation and oxidative stress are significantly improved after knockdown of Fabp1, our data also supports this result." (PMID 38036981, 2023). "Based on our observations, when insulin resistance or fatty liver disease occurs, the expression of liver-abundant FABP1 is inhibited as a compensatory mechanism." (PMID 37740216, 2023). "FABP1 activity changed significantly in the occurrence and development of fatty liver, liver cirrhosis, liver cancer and other liver diseases." (PMID 36005631, 2022). "have found that Fabp1 KO mice are susceptible to oxidative stress in early-stage alcoholic liver and that FABP1 levels were inversely correlated with the severity of fatty liver." (PMID 35460694, 2022). "A recent study in human MAFLD patients found higher levels of plasma FABP1 correlated with the degree of hepatic steatosis." (PMID 36148775, 2022). "FABP1 expression increased significantly with the formation of fatty liver and was correlated with the degree of hepatic steatosis, proving that serum FABP1 levels play an important role in NAFLD using a mouse model of NAFLD." (PMID 36277716, 2022). "More specific hepatocyte targeting using adenoviral vectors to knock down FABP1 demonstrated protection from dietary-induced hepatic steatosis and inflammation." (PMID 36148775, 2022). "FABP1 knockout mice are protected against dietary-induced hepatic steatosis; however, altered energy utilization exhibited by the global loss of FABP1 is a confounding factor in these experiments." (PMID 36148775, 2022). "IL-6 can regulate the development of tumors by promoting the expression of specific miRNAs, and miRNAs can improve hepatic steatosis and injury by inhibiting the expression of FABP1." (PMID 34056002, 2021). "The consistently low FABP1 expression by dietary restriction, and substantially high hepatic TG compared with those in the other groups, strongly supports the role of FABP1 in the development of fatty liver." (PMID 33670590, 2021). "Studies have indicated that FFA-induced hepatic steatosis and liver injury can be improved by inhibiting FABP1 expression." (PMID 32733940, 2020).
Hepatic steatosis (continued). "Downregulation of FABP1 has been identified as the new mechanism for preventing hepatic steatosis and liver injury." (PMID 32733940, 2020). "Overall, similar to CD36, FABP1 overexpression can lead to abnormal liver functions such as dyslipidemia and hepatic steatosis." (PMID 32733940, 2020). "We also found significant downregulation of L-fabp (also known as Fabp1) in E4orf1-Tg mice, which has anti-obesity, anti-hepatic steatosis, and anti-hyperglycemic effect in HF-fed mice." (PMID 32286259, 2020). "In addition, overexpression of DDAH1 in hepatocytes exacerbated hepatic steatosis in fasted mice, coinciding with FABP1 upregulation and autophagy inhibition." (PMID 42058454, 2025). "In conclusion, our results indicate that maintenance of hepatic GSTA1 levels leads to a decrease in FABP1 levels, thereby improving hepatic steatosis, which represents an interesting approach for exploring GSTA1 stabilizers or enhancers as a new class of drugs against MASLD in the future." (PMID 38791126, 2024). "Silencing of FABP1 can ameliorate hepatic steatosis, inflammation, and oxidative stress." (PMID 36277716, 2022). "FABP1 plays an important role in fatty acid uptake in HepG2 cells, leading to hypothesis that FABP1 may contribute to liver steatosis." (PMID 35252766, 2022). "However, SR treatment attenuated HFD-induced hepatic steatosis by suppressing TG contents and the expression of fatty acid transport- and lipogenesis-related genes including Fabp1, Fabp4, Slc27a5, Pparg, Mlxipl, Srebf1, Srebf2, Fas, Dgat1, and Dgat2." (PMID 35454963, 2022). "Notably, silencing FABP1 decreased hepatic steatosis, inflammation, and oxidative stress in a mouse model of nonalcoholic fatty liver disease (NAFLD)." (PMID 35252766, 2022). "Targeting FABP1 expression in the liver could be beneficial as a medical treatment for fatty liver disease." (PMID 35140289, 2022). "In line are other valuable studies which have demonstrated on FABP1 gene-ablated mice that the protein could protect against age-, diet- or Western-diet induced obesity and hepatic steatosis." (PMID 30993401, 2019). "FABP-1 null mice demonstrate age dependent weight gain, though may be protected from obesity and hepatic steatosis when fed a saturated fat diet." (PMID 21251264, 2011). "Overexpression of murine FABP1 is associated with increased LCFA uptake and hepatic TG levels, while FABP1−/− mice exhibit decreased hepatic triglyceride content with altered FA uptake kinetics, with protection against diet-induced obesity and hepatic steatosis." (PMID 26439934, 2015). "Compared with hepatocyte organoids, hepatic steatosis organoids had higher expression of the relevant markers such as perilipin 2 (PLIN2) and fatty acid binding protein 1(FABP1), which indicated the effective establishment." (PMID 39773638, 2025). "The investigators found that HFD-induced hepatic FABP1 acetylation levels were downregulated in mice after AEGL treatment, resulting in significant improvement in hepatic steatosis." (PMID 37239836, 2023). "At the molecular level, we have discovered metabolic pathways by which Dyrk1b induces hepatic steatosis (a) by activating mTORC2 and augmenting DNL and (b) by upregulating Fabp1 and CD36 and increasing FA influx into the liver." (PMID 34855620, 2022). "Future in-depth studies on how lysine acetylation affects the function of ECHD, ACOX1, and FABP-1 could shed light on the etiology of drug-induced fatty liver disease and the potential therapeutic usage of uridine to modulate liver lipid metabolism and prevent drug-induced fatty liver." (PMID 24475249, 2014). "Clinical studies have demonstrated overexpression of FABP1 in patients with obesity and hepatic steatosis compared to obese individuals without liver steatosis." (PMID 39859069, 2025). "The transcripts of ACACA, FASN, SCD, FADS2 and FABP1 in chickens with fatty liver were significantly increased compared with those in chickens without fatty liver." (PMID 29642504, 2018).
Hepatic steatosis (continued). "Therefore it is likely that under the regulation of FOXA2 and Nrf2 diminished endogenous ALR levels in hepatic steatosis result in altered expression of lipid metabolizing genes such as ELOVL6, SCD1, CPT1α as well as FABP1." (PMID 28877220, 2017). "The zebrafish homolog of human FABP1, fabp1b, is required for liver development; however, the relationship between fabp1b and hepatic steatosis has not been reported." (PMID 26052340, 2015).
Obesity (51 papers, 2009 to 2025). Accumulation of substantial excess body fat. "Multivariable-adjusted association of serum FABP1 levels and hyperuricemia in patients with obesity." (PMID 36277716, 2022). "This suggests that obesity-associated Fabp1 upregulation is promoted by fatty acids via the PPARα and TBK1–IKKε–IRF3 pathways." (PMID 36400935, 2022). "Taken together, these results suggest that the decrease in FABP1 protein observed in placentas from women with pre-gestational obesity is, to some degree, associated with the increase in neuroprostanes and isoprostanes observed in these placentas." (PMID 34444927, 2021). "Among all the polymorphisms which have been tested for their relationship with obesity and type 2 diabetes within the FABP1 gene, the functional mutation rs2241883 (p.Thr94Ala) has been the most studied." (PMID 22396741, 2012). "Other findings suggest that increased FABP1 expression is associated with insulin-dependent diabetes and gestational diabetes in humans, streptozotocin-induced diabetes or obesity in rats, and type 1 diabetes in mice." (PMID 23144966, 2012). "We investigated the association of serum FABP1 levels with obesity and insulin resistance in Chinese young people under 30 years old." (PMID 23144966, 2012). "In conclusion, we provided clinical evidence that serum FABP1 levels were positively associated with obesity and insulin resistance." (PMID 23144966, 2012). "Moreover, NTS deficiency improves AMPK signaling and FABP1 expression in conditions of obesity and aging." (PMID 40451927, 2025). "In Model 1, with BMI and age as additional covariables, we observed a statistically significant association between serum FABP1 levels and the risk of hyperuricemia in patients with obesity (Odds ratio [OR], 95% confidence interval [CI] = 1.023, 1.001–1.046, P = 0.048)." (PMID 36277716, 2022). "Alternatively, it is possible that obesity may cause resistance to FABP1 actions, leading to its compensatory up-regulation." (PMID 23144966, 2012). "FABP1 was positively associated with UA and may be a risk factor for hyperuricemia in obesity." (PMID 36277716, 2022). "In addition, it is possible that obesity may cause resistance to the action of FABP1 leading to its compensatory up-regulation." (PMID 32038102, 2020). "From our data, it appears that FABP1 is the critical player in the development of obesity and is affected by NTS." (PMID 40451927, 2025). "Our findings indicate that neurotensin inhibits AMPK and increases FABP1 in small intestinal epithelial cells under conditions of obesity." (PMID 40451927, 2025). "The increased expression of fatty acid transporters such as CD36 and fatty acid-binding protein 1 (FABP1) are increased in obesity and drive increased pathway expression, which increases GC metastasis." (PMID 38248845, 2024). "We aimed to evaluate the correlation between serum FABP1 and hyperuricemia in patients with obesity before and after laparoscopic sleeve gastrectomy (LSG)." (PMID 36277716, 2022). "In contrast, two animal studies 36,37 demonstrated that FABP1-/- mice were protected against obesity when fed a high-fat diet." (PMID 32038102, 2020). "The levels of the LPL and FABP1 mRNAs in the liver were determined to elucidate the role of hepatic fat metabolism in obesity." (PMID 31211018, 2019). "Obesity is characterized with increased expression of genes involved in lipid metabolism and inflammation, so we also examined several obesity-associated genes, including TLR-4, GPR40 and 43, Fabp1, Scd1, and Mttp." (PMID 27599699, 2016). "The purpose of the present study was to evaluate the association between specific SNPs and haplotypes of the FABP1-4 genes and DM2, obesity and abdominal obesity in two independent populations." (PMID 22396741, 2012). "Neurotensin deficiency preserves AMPK and FABP1 levels, thus attenuating some of the negative effects of obesity and aging." (PMID 40451927, 2025).
Obesity (continued). "Additionally, the lower expression of FABP1 in pregnant women with GDM would be in line with previous studies that have been performed on women with obesity." (PMID 36768809, 2023). "Therefore, we aimed to evaluate the correlation between serum FABP1 and hyperuricemia in patients with obesity before and after LSG." (PMID 36277716, 2022). "Similarly, obesity triggered increased expression of the liver-specific fatty acid transporter Fabp1 in hepatic cap ECs and of fatty acid transporters Fabp4, Cd36, Fabp5, Dbi and Lpl in art and ven ECs from AT." (PMID 36400935, 2022). "Our previous research also found serum FABP1 levels were correlated closely with obesity." (PMID 36277716, 2022). "Newberry found that, compared with wild-type mice, the FABP1-gene knockout mice could significantly inhibit diet-induced obesity and reduce the development of fatty liver when fed a diet rich in fatty acids." (PMID 36277716, 2022). "Therefore, serum FABP1 levels can change a variety of metabolic factors and regulate the pathogenesis of obesity." (PMID 36277716, 2022). "FABP1 comprises 127 amino acids with a molecular weight of approximately 14–15 kDa, can regulate the expression of some essential genes involved in lipid metabolism, and is related closely to a variety of metabolic syndromes, such as obesity, NAFLD, and IR." (PMID 36277716, 2022). "Cumulative evidence suggests the positive correlation of FABP-1 with obesity, diabetes and NASH." (PMID 32933141, 2020). "Interestingly, chronic CS exposure also enhanced Fapb1 and Apoc2 expression in the gut of lean mice and had additive effect on obesity-induced Fabp1 and Apoc2 expression." (PMID 32244932, 2020). "Consistent with a key role for FABP1 localisation in explaining the altered FA metabolism modulated by GADD45β expression, FABP1 is a highly abundant protein in the liver which has a role in cellular uptake of FAs and affects the development of insulin resistance in obesity." (PMID 27137487, 2016). "They showed that some lipid metabolism-related genes (i.e., Mod1, Cyp4a10, Hmgcs2, Acot1, Acot2, Pdk4, Acaa1b, Cpt1, Fabp1, and Acadl) were significantly up-regulated in the intestine of both A/J (obesity-resistant) and C57BL/6J (obesity-prone) mice fed with high fat diet." (PMID 26861690, 2016). "Using whole‐body knockout mice as well as liver/hepatocyte‐specific gain‐ and loss‐of‐function strategies, we revealed a role for liver GADD45β in the coordination of liver fatty acid uptake, through cytoplasmic retention of FABP1, ultimately impacting obesity‐driven hyperglycaemia." (PMID 27137487, 2016). "As another lipid chaperon of FABP family, L-FABP (called FABP1 hereafter) may also serve as an etiological mediator of obesity-related metabolic diseases." (PMID 23144966, 2012). "Serum FABP1 correlates positively with obesity and insulin resistance in Chinese young adults." (PMID 23144966, 2012). "Therefore, little consensus has been reached on the potential role of FABP1 in energy metabolism and obesity." (PMID 23144966, 2012). "Thus, FABP1−/− mice appear to present a model of metabolically healthy obesity." (PMID 37207357, 2023). "Hence, we speculate that the decreased content of FABP1 found in placentas from women with pre-gestational obesity might have affected placental function beyond just lipid transport." (PMID 34444927, 2021). "However, discrepancies in the correlation between FABP1 and obesity have been reported." (PMID 32038102, 2020). "Because a review suggests that FABP1 could have an important role in preventing age- or diet-induced obesity, the “paradoxical” elevation of serum FABP1 in obese subjects might be a compensatory up-regulation of the human body to counteract the metabolic stress imposed by obesity." (PMID 23144966, 2012). "Recent studies have identified an intestinal PPARα-fatty acid-binding protein 1 (FABP1) axis that regulates dietary fatty acid uptake and influences obesity and MASLD progression." (PMID 41438090, 2025).